ETV6 (ETS variant transcription factor 6)
Diseases named in the same sentence as ETV6 in open-access papers (continued):
Sharing a sentence is not in itself a finding about the gene and the disease.
glioma (11 papers, 2020 to 2025). A benign or malignant brain and spinal cord tumor that arises from glial cells (astrocytes, oligodendrocytes, ependymal cells). "Another patient with an Infant-type hemispheric glioma with a ETV6::NTRK3 fusion was treated with larotrectinib and demonstrated response to treatment with tumor regression and clinical stability." (PMID 41331048, 2025). "In one tumor of 59 glioma specimens, one rearrangement with 6225 fusion reads mapped fusing exon 5 of the gene ETV6 to exon 15 of NTRK3 was identified in oligodendroglioma–grade II, IDH-mutated and 1p19q co-deleted at frequency of 1.69%." (PMID 39087020, 2024). "Further, the silencing of ETV6 in glioma cell lines induced apoptosis, attenuated proliferation, inhibited clonogenic growth, migration, and invasion." (PMID 36292767, 2022). "ETV6 silencing in glioma cells led to increased apoptosis or decreased proliferation, clonogenicity, migration, and invasion." (PMID 36292767, 2022). "We then examined the effect of ETV6 knockdown on glioma cellular behaviors and found that ETV6 silencing induced apoptosis and reduced proliferation, clonogenicity, migration, and invasion." (PMID 36292767, 2022). "The effect of ETV6 knockdown on glioma cell proliferation (EdU), viability (AnnexinV labeling), clonogenic growth (colony formation), and migration/invasion (transwell assays) in GBM cells was tested." (PMID 36292767, 2022). "Herein, we examined ETV6 expression in 192 cases of glioma from Chinese and US cohorts, followed by validation in 1071 cases of glioma from public datasets of TCGA and REMBRANDT." (PMID 36292767, 2022). "To investigate this, we first performed ETV6 knockdown in U251 glioma cells by small interfering RNA-mediated gene silencing (siETV6) (IDT, TriFECTa® RNAi Kit, Coralville, CA, USA)." (PMID 36292767, 2022). "Four cases of CNS tumors were diagnosed: a ganglioglioma, a choroid plexus carcinoma, a CNS GCT, and an infantile high-grade glioma with classical ETV6/NTRK3 fusion." (PMID 35565372, 2022). "Considering tumor type (oligodendroglioma vs. astrocytoma) also has a significant effect on the survival of glioma patients, and we compared the expression of ETV6 between them using TCGA dataset." (PMID 36292767, 2022). "ETV6 was a poor prognostic factor, with elevated expression that positively correlated with glioma grade and negatively correlated with patient survival." (PMID 36292767, 2022). "We then silenced ETV6 in U251 and A172 glioma cells using lentiviral short hairpin RNA (shETV6) with sufficient knockdown efficiency." (PMID 36292767, 2022). "In this study, we investigated the role of ETV6 in GBM tumor progression by first examining its expression in 192 gliomas, which demonstrated high ETV6 expression in GBM and correlation with poor survival." (PMID 36292767, 2022). "Using microarray datasets from patients with different grades of glioma, we have analyzed the expression profiles of various ETS genes, and have identified ETV1, ELK3, ETV4, ELF4, and ETV6 as novel biomarkers for the identification of different glioma grades." (PMID 33671331, 2021). "The mRNA expression of ETV6 was positively correlated with glioma grade in REMBRANDT database." (PMID 36292767, 2022). "ETV6 expression was significantly correlated with glioma grade." (PMID 36292767, 2022). "ETV6 expression is an unfavorable prognostic factor in glioma." (PMID 36292767, 2022). "Finally, we performed RNA sequencing and Western blot to indicate that the role of ETV6 in glioma was likely mediated partially via the PI3K-AKT and Ras-MAPK pathways." (PMID 36292767, 2022). "Our data suggest that ETV6 may be a putative therapeutic target for glioma that merits further investigation." (PMID 36292767, 2022). "Moreover, we subdivided the 58 gliomas into low (staining intensity of 0–2) and high (staining intensity > 2) ETV6 groups in LGG and GBM, respectively." (PMID 36292767, 2022).
glioma (continued). "Furthermore, both ELF4 and ETV6 expressions are downregulated at grade 2 glioma, but upregulated at increasing levels in grades 3 and 4, indicating that these genes can also be utilized as additional molecular determinants to distinguish glioma grades." (PMID 33671331, 2021). "ETV6 was consistently highly expressed in GBM, with its expression positively correlated with glioma grade and negatively correlated with survival." (PMID 36292767, 2022). "Two reports describe patients suffering from a low-grade glioma (LGG), one with a NACC2:NTRK fusion showing more than 50% reduction in tumor volume and an ETV6:NTRK3-fused tumor with complete remission upon treatment with larotrectinib." (PMID 33353026, 2020). "Interestingly, the expression of ETV6 is significantly positively related to the expression of EGFR and VEGF in glioma, especially in GBM." (PMID 36292767, 2022).
thyroid cancer (11 papers, 2014 to 2025). "The rearrangements of ETV6 were also observed in radiation-associated thyroid cancer." (PMID 30706161, 2019). "Beyond these considerations, it must be highlighted that the ETV6/NTRK3 is the most frequent structural rearrangement involving NTRK genes described in thyroid cancer; therefore, a screening based on IHC testing could miss essential information in thyroid tumors." (PMID 35806472, 2022). "For example, the ETV6::NTRK3 fusion gene (breakpoints located in introns 4 and 13, respectively) was identified in thyroid cancer by the OncoGuide NCC Oncopanel System which was not covered by FoundationOne CDx." (PMID 38925616, 2024).
lymphoid neoplasm (10 papers, 2018 to 2025). A neoplasm composed of a lymphocytic cell population which is usually malignant (clonal) by molecular genetic and/or immunophenotypic analysis. "ETV6 is the major target of translocations involving 12p13 in hematopoietic malignancies, and is frequently rearranged in both myeloid and lymphoid neoplasms." (PMID 29541391, 2018). "Finally, the possible contribution of germline mutations, including DDX41, RUNX1, ETV6, ANKRD26, and POT1, which have been associated with the occurrence of both myeloid and lymphoid neoplasms, is an intriguing point to be explored in future studies." (PMID 34733777, 2021). "To enhance understanding of myeloid/lymphoid neoplasms with ETV6::ABL1 fusion, we retrospectively analyzed the clinical data of a patient with myeloid lymphoid neoplasms with ETV6::ABL1 fusion." (PMID 40887424, 2025).
chronic myeloid leukemia (9 papers, 2013 to 2026). "We report a case of a 65-year-old man diagnosed with a ETV6::PDGFRB-translocated MLN, presenting as atypical chronic myeloid leukemia (aCML), who exhibited a brief response with development of resistance to imatinib." (PMID 41278291, 2025). "Because the ETV6::ABL1 rearrangement shares the constitutive activation of the same tyrosine kinase with the BCR::ABL1 rearrangement, it has the peculiarity of being the one that most closely resembles chronic myeloid leukemia (CML)." (PMID 38254826, 2024). "These potentially include patients with fusions of JAK2 with PCM1, ETV6 and BCR, T-cell large granular lymphocytic leukaemia, chronic lympho-proliferative disorders of natural killer cells, Waldenstrom’s Macroglobulinaemia, chronic myeloid leukaemia and chronic lymphocytic leukaemia." (PMID 26131691, 2015).
colorectal cancer (8 papers, 2016 to 2025). A primary or metastatic malignant neoplasm that affects the colon or rectum. "We find a variant at 12p13.2 associated with colorectal cancer risk (rs2238126 in ETV6, P=2.67 × 10−10)." (PMID 27145994, 2016). "Our findings highlight the potential importance of genetic variation in ETV6 conferring susceptibility to colorectal cancer." (PMID 27145994, 2016). "Based on these data, the ETV6 gene can be considered to be a susceptibility gene for colorectal cancer, although the detailed molecular mechanisms underlying a regulatory role of ETV6 in colorectal cancer remain to be further elucidated." (PMID 27145994, 2016). "In summary, we identified a previously unknown colorectal cancer susceptibility locus in the ETV6 gene at 12p13.2." (PMID 27145994, 2016). "The SNP rs2238126 G allele may attenuate the regulation of ETV6, which in turn is associated with increased risk of colorectal cancer, most likely by altering the binding affinity of transcriptional enhancer MAX." (PMID 27145994, 2016). "Notably, rs2238126 in ETV6 was not related to previously implicated genes, thus supporting the role of ETV6 as a potentially independent risk factor for colorectal cancer." (PMID 27145994, 2016). "However, the low expression of ETV6 is linked to a high risk of colorectal cancer." (PMID 36292767, 2022). "The fusion that involved ETS variant of transcription factor 6 (ETV6) and NTRK3 was found, for example, in congenital fibrosarcoma, congenital mesoblastic nephroma, PTCs and colorectal cancer." (PMID 38144536, 2023). "Next, we examined the mRNA expression levels of ETV6 in 112 pairs of colorectal cancer tumours and their adjacent normal tissues and found significantly decreased ETV6 expression in tumour tissues compared with their adjacent normal tissues (PWilcoxon<0.001)." (PMID 27145994, 2016). "We randomly selected 67 pairs of colorectal cancer patients for immunohistochemical staining for ETV6 and found that ETV6 was highly expressed in the cytoplasm in tumours, whereas its expression in normal epithelial cells was primarily localized to the nuclei." (PMID 27145994, 2016). "In the “Other tumors group” four rearrangements involving BRAF gene were detected (three melanoma: BRAF::CNNM2, BRAF::ERC1, BRAF::MAD1L1 and one pancreatic adenocarcinoma BRAF::SND1), but also one ETV6::NTRK3 (colorectal cancer) and one FGFR3::TACC3 (urothelial cancer)." (PMID 37708140, 2023). "ETV6 is a TF with decreased expression in colorectal cancer compared with in the normal colon, and genetic variation in ETV6 may confer colorectal cancer susceptibility." (PMID 37468586, 2023). "The identified connections showed that there was a higher-than-expected degree of connectivity, with a significance of PGRAIL<0.05 being observed for TGFB1, SMAD7 and BMP4. rs2238126 in ETV6 presented a weaker than expected connection with other genes reported in previous GWAS of colorectal cancer." (PMID 27145994, 2016). "We measured the ETV6 mRNA and protein expression levels in colorectal cancer cell lines and observed that ETV6 expression was not detectable in the SW480 cell line." (PMID 27145994, 2016).
Ewing sarcoma (8 papers, 2022 to 2025). A small round cell tumor that lacks morphologic, immunohistochemical, and electron microscopic evidence of neuroectodermal differentiation. "For example, a synthetic DNA oligonucleotide-based PROTAC, d(GGAA)3s, has been developed to selectively degrade ETV6 in Ewing sarcoma cells." (PMID 41228232, 2025). "We demonstrated that the ETS TF ETV6 is a selective dependency in Ewing sarcoma because it antagonizes the transcriptional activity of EWS–FLI at ETS motifs." (PMID 36658220, 2023). "In contrast to selective TF dependencies that reinforce the oncogenic programmes of mutant TFs in other cancer types, the repressive activity of ETV6 constrains EWS–FLI gene activation at 5′-GGAA-3′ repeat enhancers to promote Ewing sarcoma growth." (PMID 36658220, 2023). "We validated an ETV6 dependency in three cell lines of Ewing sarcoma, A673, EW8 and TC32, via CRISPR–Cas9 disruption." (PMID 36658220, 2023). "Here we describe the results of a genome-scale CRISPR–Cas9 screen revealing that the wild-type ETS TF ETS variant 6 (ETV6; also known as TEL) is a crucial Ewing-sarcoma-selective TF dependency." (PMID 36658220, 2023). "At 6 h, the majority of differentially expressed genes were upregulated, which suggests that ETV6 acts predominantly as a transcriptional repressor in Ewing sarcoma." (PMID 36658220, 2023). "Notably, however, our experiments using an ETS DBD-deleted mutant of ETV6, with an intact PNT domain, demonstrated that the DNA-binding activity of ETV6 is crucial to its function in Ewing sarcoma." (PMID 36658220, 2023). "Independent but complementary studies from Vakoc and Stegmaier identify and characterize a role for ETV6 in counteracting the transcriptional activity of EWS–FLI during Ewing sarcoma development, which may be targeted for therapeutic benefits." (PMID 36658220, 2023). "Whereas wild-type ETV6 expression rescued ETV6 knockout, expression of the mutant ETV6 did not, which suggests that the specific activity of ETV6 on chromatin is crucial to its function in Ewing sarcoma." (PMID 36658220, 2023). "We next asked whether the antagonistic relationship between EWS–FLI and ETV6 is responsible for the dependency of Ewing sarcoma cells on ETV6." (PMID 36658220, 2023). "In the Ewing sarcoma cell lines A673 and EW8, we exogenously expressed ETV6 carboxy-terminally tagged with FKBP12F36V and a human influenza haemagglutinin (HA) epitope." (PMID 36658220, 2023). "By binding to ETV6, d(GGAA)3s facilitates its ubiquitination and proteasomal degradation, leading to suppressed cell proliferation and increased sensitivity to chemotherapy in Ewing sarcoma models." (PMID 41228232, 2025). "Notably, ETV7, the homologue of ETV6, is not expressed in Ewing sarcoma cells, and we did not observe strong changes in the expression of other ETS TFs with ETV6 loss." (PMID 36658220, 2023). "Instead, our discovery that ETV6 constrains EWS–FLI activity highlights a distinct, but equally central, epigenetic mechanism that drives tumour growth and reveals an unexpected contrast between Ewing sarcoma and other paediatric tumours in which CRCs are functionally dominant." (PMID 36658220, 2023). "The other two NTRK gene fusions in pediatrics were an LPP1::NTRK2 fusion (Ewing’s sarcoma), and a RAD51B::NTRK3 (PTC); we did not identify ETV6::NTRK3, TPR::NTRK1 – NTRK gene fusions were more commonly reported among pediatrics with solid tumors." (PMID 38967220, 2024).
platelet disorder (8 papers, 2020 to 2026). "Genes involved in germline predisposition and preexisting platelet disorders include RUX1, ANKRD26, and ETV6." (PMID 36534659, 2022).
salivary gland carcinoma (8 papers, 2022 to 2025). A carcinoma that arises from the major or minor salivary glands. "In this case series report, the demographic, clinical, histopathologic and ETV6 break-apart FISH patterns of 7 salivary gland carcinomas are presented." (PMID 39101978, 2024). "A high prevalence of ETV6::NTRK3 in salivary gland carcinoma in the present study is probable as most head and neck cancers were identified as salivary gland carcinoma (72.7%) and the rest were unclassified." (PMID 38925616, 2024). "The search returned 10 manuscripts published between 2012 and 2022, describing 51 salivary gland carcinomas with an atypical ETV6 FISH result." (PMID 39101978, 2024). "Secretory carcinoma of the salivary glands (formerly known as mammary analog secretory carcinoma) is a low-grade salivary carcinoma characterized by a specific ETV6 rearrangement." (PMID 36186229, 2022). "Salivary gland carcinomas share the same histological and immunohistochemical features as mammary gland secretory carcinomas, including mutated ETS 6 (ETV6) gene and translocation of neurotrophic receptor tyrosine kinase type 3 (NTRK3), which regulate cell growth and differentiation." (PMID 40391352, 2025). "Additionally, fusions observed in other subtypes of salivary gland carcinoma, such as ETV6::NTRK3 and NCOA4::RET described in secretory carcinoma and intraductal carcinoma, respectively, have been reported in SDC without any histologic evidence of these other tumor types." (PMID 41357819, 2025). "ETV6::NTRK3 was the only NTRK fusion gene detected in head and neck cancer and is known to be common in salivary gland carcinoma." (PMID 38925616, 2024). "The association of atypical ETV6 FISH signals with epidemiological, clinical and prognostic parameters in salivary gland carcinomas has not been fully characterized." (PMID 39101978, 2024).
salivary gland tumor (8 papers, 2015 to 2025). "Among salivary gland tumors, although ETV6 rearrangements have been exclusively associated with SC, alterations in ETV6 copy number have been reported in other malignant salivary gland neoplasms." (PMID 39101978, 2024). "In the last decade, advances in molecular techniques have demonstrated recurrent genetic alterations in some salivary gland tumors, including the fusion of genes such as ETV6 in secretory carcinoma, MYB and MYBL1 in adenoid cystic carcinoma, and MAML2 in MEC." (PMID 39958930, 2025). "In a comparative study assessing ETV6 gene status in salivary gland tumors, almost all cases of high-grade salivary duct carcinomas (11/12, 91.7%) demonstrated increased ETV6 fusion signals, indicative of gain of the ETV6 gene." (PMID 39101978, 2024). "The ETV6::NTRK3 fusion – detected in a single patient with a salivary gland tumor – has been commonly reported by others." (PMID 38967220, 2024). "The authors present a series of salivary gland malignancies with assessment for rearrangement of the ETV6 (12p13) locus using a break-apart probe and review the literature on salivary gland tumors with an atypical ETV6 FISH result." (PMID 39101978, 2024). "The nosology of salivary gland tumors harboring deletion of one ETV6 fusion signal and demonstrating apical membranous staining for DOG1 around tumor lumina thus remains to be clarified." (PMID 39101978, 2024). "In the context of salivary gland tumors, ETV6::NTRK3 fusion is specific for secretory carcinoma (SC)." (PMID 37415052, 2023). "In the same line, a high-grade salivary gland tumor composed of expansile, centrally necrotic nests composed of AR-positive and S100-negative apocrine-type cells with an ETV6::NTRK3 fusion was recently interpreted as salivary duct carcinoma with an unusual genetic background." (PMID 37415052, 2023). "Moreover, histomorphological and immunohistochemical characteristics are key to distinguishing SCSGs from other salivary gland tumors, with the detection of ETV6 translocation considered the gold standard for diagnosis." (PMID 34811395, 2021). "Although molecular testing for ETV6 gene rearrangement is characteristic of MASC and has not been shown in any other salivary gland tumor, a particular challenge arises when such testing is unavailable, or when molecular testing for ETV6 gene rearrangement is negative in a suspected case of MASC." (PMID 31929931, 2019). "ETV6 gene rearrangement is the molecular hallmark of secretory carcinoma (SC), however; the nature, frequency, and clinical implications of atypical ETV6 signal patterns by fluorescence in situ hybridization (FISH) has not yet been systematically evaluated in salivary gland neoplasms." (PMID 39101978, 2024). "ETV6-NTRK3 and ETV6-RET translocation was found to be specific for secretory carcinoma (a.k.a. mammary analogue secretory carcinoma, MASC) and has not been documented in any other salivary gland tumor." (PMID 33237469, 2021).